IL6 (interleukin 6)
Diseases named in the same sentence as IL6 in open-access papers (continued):
Sharing a sentence is not in itself a finding about the gene and the disease.
Sepsis (continued). "Finally, further in vitro and in vivo experiments should be conducted in future studies to elucidate the regulatory mechanisms and functional roles of MASP-1, CD8 T cells, and IL6/JAK/STAT3 signaling pathways in trauma and sepsis." (PMID 38384415, 2024). "Consequently, our results highlight the remarkable ability of LBT to downregulate the production of IL-6, TNF-α, and IL-1β while alleviating LPS-induced sepsis through its impact on macrophage-mediated inflammatory cytokine production." (PMID 38799158, 2024). "Levels of serum IL-6, TNF-α, and IL-10 in sepsis mice treated with anti-PD-L1 antibody significantly declined at 24 (P = 0.004), 48 (P = 0.006), and 72 h (P = 0.005), respectively; there were no significant changes at other time points, showing no statistical significance." (PMID 37776443, 2024). "In animal models, it has been demonstrated that OMVs derived from intestinal E. coli are causative microbial signals in the pathogenesis of systemic inflammatory response syndrome (SIRS) and sepsis-induced lethality through the systemic induction of TNF-α and IL-6." (PMID 39201409, 2024). "One study suggests that IL-6 predicts treatment success in patients with non-surgical sepsis more effectively within first 48–72 h than PCT or CRP." (PMID 39589972, 2024). "Multiple studies found that IL-6 was only able to differentiate between sepsis and no sepsis at the onset and had limited potential for diagnosis later during the course of sepsis." (PMID 38671704, 2024). "Furthermore, studies have demonstrated a higher discriminatory power between severe sepsis and SIRS when using PCT and IL-6, with a reported area under the ROC of 0.923." (PMID 39589972, 2024). "Additionally, the levels of pro-inflammatory cytokines, such as IL-17A, IL-6, and TNF-α, were notably elevated in the Sepsis+shPIMI group, whereas the anti-inflammatory cytokine IL-10 was reduced." (PMID 39108261, 2024). "Therefore, this study constructed a nomogram of TAPSE/PASP combined with biochemical markers IL-6 and LAC to diagnose the prognosis of sepsis patients." (PMID 38961249, 2024). "We speculate that cytokines such as IL-6, which has a thermogenic effect in chronic situations, reduces BAT thermogenesis in acute conditions like sepsis due to its potent proinflammatory effects." (PMID 39522078, 2024). "Sepsis was demonstrated to upsurge the expression of NF-kB and repress Nrf-2 signaling pathway, which further stimulates the expression of TNF-α, IL-1β, and IL-6." (PMID 37548662, 2024). "(CEF and PTX) combined but not CEF alone decreased IL-6 tissue concentrations compared to untreated sepsis mouse pups." (PMID 39963236, 2024). "The measurement of TNF-α and IL-6 levels in lung tissue by ELISA revealed that BRD3308 mitigated the release of inflammatory cytokines, which indicated that BRD3308 had a significant anti-inflammatory effect on sepsis-induced ALI." (PMID 39224841, 2024). "Sepsis is marked by an initial and intense systemic inflammatory response syndrome (SIRS), commonly referred to as a cytokine storm, characterized by overexpression of inflammatory mediators like IL-1β, IL-6, and IL-8." (PMID 38397855, 2024). "More than 200 biomarkers of sepsis are described, such as C-reactive protein (CRP), procalcitonin, calprotectin, and some inflammatory cytokines, e.g., tumor necrosis factor (TNF)-α and interleukin (IL)-6, IL-8, IL-10, and IL-12." (PMID 38003758, 2023). "In addition, NRF2-mediated transcription of antioxidant enzymes reduces ROS levels and suppresses neutrophil production of IL-6 and TNF-α in sepsis models." (PMID 36671034, 2023). "Overall, the pilot study of Tsujinaka and colleagues showed that transgenic mice chronically overexpressing IL-6 exhibit a marked muscle atrophy; however, the knockout of IL-6 was not sufficient to prevent sarcopenia in a sepsis mouse model." (PMID 37047427, 2023). "The sepsis-induced renal damage led to an increase in TNF, TNF receptor, and IL-6 levels." (PMID 36937479, 2023).
Sepsis (continued). "In addition, in another study, we created sepsis by cecal ligation puncture method in rats, TCE significantly reduced TNF-α, IL-1β, IL-6, TOS, OSI levels, expression of caspase-3 and NF κB and increased TAS values." (PMID 37476882, 2023). "We did not identify a robust effect on sepsis when instrumenting gp130, although there is much less evidence that genetic variation at this locus affects IL-6 signalling." (PMID 36716318, 2023). "Using a sepsis-induced acute lung injury (ALI) model, the authors determined that PDX ameliorated histopathological changes in lung tissue, reduced bacterial load, pulmonary edema, PMN migration, and production of IL-1β, IL-6, TNF-α, and MCP-1." (PMID 37446699, 2023). "Most importantly, 2K4L showed remarkable protection in A. baumannii-infected sepsis mice by downregulating the expression of proinflammatory signaling pathway proteins, leading to a decrease in the production of the proinflammatory factors TNF-α and IL-6." (PMID 37942076, 2023). "Some studies have shown that the levels of characteristic cytokines such as TNF‐α, IL‐6, IL‐1β, IL‐1α, IL‐12, IL‐17, CXCL1, CXCL2, MCP‐1, IL‐8, CXCL10, GM‐CSF, M‐CSF, and G‐CSF in patients with septicemia are significantly higher than those in normal volunteers." (PMID 36684101, 2023). "The classic markers of sepsis, such as SOFA, CRP, PCT, and IL-6 on Days 0, 3, and 5 were compared." (PMID 37510189, 2023). "For instance, the combination of PCT and CRP has shown promise in diagnosing BSI, particularly for sepsis, while IL-6 has proven useful in distinguishing sepsis from non-infectious systemic inflammatory response syndrome." (PMID 37986183, 2023). "In a recent report, in mice with LPS-induced sepsis, G-Rg6 suppressed TNF-α, IL-6, and IL-1β and increased IL-10, thereby inducing the expression of miR-146a and acting as an anti-inflammatory agent in bone marrow-derived macrophages, which are known to regulate inflammatory responses." (PMID 38202632, 2023). "To explore whether SLAMF7 regulate the production of proinflammatory cytokines induced by sepsis in vivo, we determined the concentrations of TNF-α, IL-1β, and IL-6 in serum and supernatants of liver, lung, and PL." (PMID 36749634, 2023). "According to a clinical study involving 81 patients with severe pneumonia complicated with sepsis, the expression levels of TNF-α, IL-6, IL-8, and other inflammatory factors in the group that received Tα1 under the basal epithelium were significantly reduced compared with those in the control group." (PMID 36816800, 2023). "Furthermore, administering AM and AMBP-1 following sepsis induction in rats reduced inflammatory indices including circulating TNF-α, IL-6, and IL-1β." (PMID 37113606, 2023). "Therefore, we next investigated a relation between IL-6 and PAI-1 at 24 h to find an indirect role of PAI-1 in hemodynamic profile of severe sepsis and septic shock." (PMID 37007795, 2023). "IL-6 was significantly increased in the serum samples of Peli1−/− (706.8 ± 43 vs. 259.7 ± 18.70; pg/mL; n = 6; p < 0.0001) and CP1KO (503.3 ± 10.59 vs. 259.7 ± 18.70; pg/mL; n = 6; p < 0.0001) sepsis groups when compared to the AMPELlTg/+ group." (PMID 37296648, 2023). "The results of the current study also confirmed that SIN could induce increased secretion of TNF-α, IL-6, and IL-1β in CLP-induced sepsis." (PMID 37388447, 2023). "In view of the arguments and evidence presented here, it is suggested that a combination of corticosteroids and/or anti-IL-6 and anti-TNF-α antibodies and GLA, DHLA, AA, EPA, DHA, along with vitamins C, B1, B6, B12, and folic acid, can prevent and suppress sepsis and other inflammatory conditions." (PMID 37759732, 2023). "From a model of MRSA infection for 24h murine sepsis, blood samples showed the vancomycin treatment down regulated Toll-like receptor signaling pathway and IL-1β production, but not IL-6 and TNF-α production." (PMID 36844408, 2023).
Sepsis (continued). "Finally, we found a significant correlation between eryptosis and other biomarkers of sepsis such as EAA, IL-6 and MPO." (PMID 37762478, 2023). "ELISA-based detection of the levels of TNF-α, IL-6, and IL-10 in the peripheral blood of mice 24 h after CLP induction revealed that cytokine content in the peripheral blood increased during the development of sepsis." (PMID 37434129, 2023). "This article constructed a mouse model of sepsis and used purified mouse neutrophils for subsequent detection experiments and found that the expression of inflammatory cytokines TNF‐α, IL‐1β, and IL‐6 in activated neutrophils was significantly upregulated, consistent with previous research." (PMID 37647440, 2023). "Recently it was shown that endothelial trans-IL-6 signaling was required for maximum expression of IL-6, IL-8, CCL2 (C–C motif ligand 2) and PAI-1 (plasminogen activator inhibitor-1), all of which are increased in patients with CRS as a result of sepsis, ARDS, burns and SARS-CoV2 infection." (PMID 36829255, 2023). "Some studies in animals have shown that dexmedetomidine could prevent sepsis-induced AKI by reducing the levels of inflammatory cytokines, such as tumor necrosis factor-alpha, monocyte chemotactic protein-1 and interleukin-6, and ameliorate renal dysfunction." (PMID 37596542, 2023). "Several biomarkers, although nonspecific, could be used as surrogate markers of the proinflammatory and anti-inflammatory states of sepsis, such as CRP, TREM, TNF-α, IL-6, IL-10 and the TNF/IL-10 ratio." (PMID 37665397, 2023). "IL-6 levels were significantly higher in mice subjected to severe sepsis compared with the group with nonsevere sepsis." (PMID 36917195, 2023). "Interleukin-6, interleukin-2, interleukin-4 and procalcitonin in KD with severe sepsis group were significantly higher than those in KD with non-severe sepsis group." (PMID 37234775, 2023). "Thirdly, C-reactive protein measurement was not available in the bacterial sepsis group, nor was measurement of cytokines such as IL-1, IL-6 or TNF-α as these biomarkers are extensively studied in sepsis, regardless of etiology." (PMID 36982221, 2023). "Our data confirm that glutamine at 10 mM before or after stimulation cannot modulate any induction effect of either LPS or HS on relative HSP90α gene expression, monocyte HSP90α protein, and supernatant IL-1β, IL-6, IL-8, IL-10, and TNF-α concentrations of PBMCs in sepsis." (PMID 36615909, 2023). "Despite the increase in inflammatory cytokines (IL-6, IFN-γ) and chemokine (MCP-1), elevated concentrations of IL-10 were detected, which functions as a temporal regulator of the transition from early reversible sepsis to the late phase of irreversible shock." (PMID 37621924, 2023). "The levels of the cytokine IL-6, considered a marker for sepsis severity, were higher in severe sepsis relative to sham or nonsevere disease, and a negative correlation between Plg and IL-6 levels during sepsis was observed." (PMID 36917195, 2023). "In the past few decades, a large number of serum (plasma) experimental tests have been conducted on sepsis patients, and the molecular markers of sepsis have been found to include C-reactive protein (CRP), procalcitonin (PCT), presepsin, interleukin-6 (IL-6), and neutrophil CD64." (PMID 36691469, 2023). "Besides, Ureaplasma infection increased the infiltration of inflammatory cells, releasing cytokines of interleukin 6 (IL-6), matrix metalloproteinase 8 (MMP8), tumour necrosis factor α (TNFα) and contributing to late-onset sepsis (LOS)." (PMID 37365524, 2023). "Furthermore, knockout of TLR4 results in decreased mortality and expression of IL-6 and TNF-α, with better global ventricular function in a sepsis animal model." (PMID 37600769, 2023). "Though we were able to reproduce the protective effect of uPAR-KO in our sepsis model, systemic levels of cytokines such as IL-6 were not significantly different between the studied strains." (PMID 37036003, 2023).
Sepsis (continued). "Recent studies have revealed that hepatic macrophages can secrete distinct sets of cytokines and chemokines, including TNF-α, IL-1β, and IL-6, which are the key mediators in systemic inflammatory response syndrome (SIRS) and the generation of hepatic acute-phase proteins during sepsis." (PMID 36768433, 2023). "In addition, sepsis significantly increased serum levels of lactate, TNF-α and IL-6, which were effectively decreased by melatonin administration." (PMID 37205094, 2023). "Compared with wild‐type mice, the TLR4 knockout decreased mortality rates, improved cardiac dysfunction, and reduced expressions of IL‐1β, IL‐6, and TNF‐α in heart tissues and decreased neutrophil infiltration in cecum ligation and puncture (CLP)‐induced sepsis mice." (PMID 38455195, 2023). "In addition, some variables with lower frequency still need to be considered, such as: Surviving Sepsis Campaign Bundles, ScvO2, BNP, TnT, PCT, IL-6, and administration time of appropriate antimicrobial therapy." (PMID 38082381, 2023). "In addition, this study found many variables that are ignored clinically, such as Surviving Sepsis Campaign Bundles, ScvO2, BNP, TnT, PCT, IL-6, and administration time of appropriate antimicrobial therapy." (PMID 38082381, 2023). "Based on this, patients with sepsis were enrolled in this study to analyze the correlation between the changes of T lymphocyte subsets, PCT, IL-6 and the severity of the disease, so as to provide a reliable reference for clinical treatment and improvement of prognosis." (PMID 36694784, 2023). "In addition, inflammatory cytokines such as interleukin-1β (IL-1β), IL-6, IL-18, tumor necrosis factor alpha (TNF-α), and interferon-gamma (IFN-γ) have been reported to play an essential role in the development of sepsis and septic shock." (PMID 37359526, 2023). "The cytokines IL-6, IL-8, IL-10 and TNF-α are established for the assessment of outcome in sepsis." (PMID 37744876, 2023). "IL-6 and CRP are often used in concert to aid in the diagnosis of sepsis." (PMID 37606448, 2023). "This feedback regulation between cytokines, as well as EFA metabolism, implies that maintaining adequate cell/tissue concentrations of GLA, DGLA, AA, EPA, and DHA is needed to suppress inappropriate and excess generation of IL-6, TNF-α, and that HMGB1 is harmful, especially in sepsis." (PMID 37759732, 2023). "Among the sepsis biomarkers, NE-SFL/NE-WY were strongly associated with PCT and IL-6, but not with presepsin or CRP." (PMID 37324133, 2023). "Sepsis-induced multiple organ injuries are accompanied by an excessive response of innate inflammation, which stimulates the secretion of multiple inflammatory cytokines, such as TNF-α and IL-6." (PMID 37251537, 2023). "Recombinant pCTS-L induced interleukin-6 (IL-6), IL-8, GRO-α/KC, GRO-β/MIP-2, and MCP-1 release in innate immune cells and moderately correlated with blood concentrations of these cytokines/chemokines in clinical sepsis." (PMID 36735789, 2023). "Given that IL-6 is an established therapeutic target and Stat3 is an emerging target in managing sepsis, this is important for understanding the working mechanism of ACT001 in sepsis." (PMID 38094883, 2023). "ICU patients with SARS-CoV-2 infection (Cohort A), grouped into increasing and decreasing RNase 1 serum levels, were evaluated for various biomarkers and scores (lactate, IL-6, PCT, CRP, sepsis-related organ failure assessment (SOFA) score, and Horowitz score) over a 14-day period." (PMID 37569802, 2023). "In our study, the plasma levels of proinflammatory cytokines IL-1β, IL-6 and TNF-α were markedly elevated in CLP group rats at 12 hours to 5 days, also demonstrating once again the successful establishment of a CLP-induced sepsis model." (PMID 37219401, 2023). "Baseline, isolated measurement of PCT, CRP, IL-6, and sCD14 has not been shown to help predict mortality in critically ill patients with sepsis." (PMID 37537680, 2023).
Sepsis (continued). "Plasma levels of Plg were significantly lower in mice subjected to severe compared with nonsevere sepsis, whereas systemic levels of IL-6, a marker of sepsis severity, were higher in severe sepsis." (PMID 36917195, 2023). "After LPS induction, supernatant IL-6 (p = 0.005), IL-8 (p = 0.01), IL-10 (p = 0.001), and MCP-1 (p = 0.029) at 24 h and IL-8 (p = 0.015), IL-10 (p < 0.001), and MCP-1 (p < 0.001) at 48 h were higher in SIRS compared to healthy control and/or sepsis." (PMID 36615909, 2023). "Indeed, pro-inflammatory cytokines, including IL-6 and TNF-α, are able to activate the coagulation cascade and to downregulate anticoagulant system in sepsis." (PMID 37569751, 2023). "Similar to the data obtained from septic mice, there was a negative correlation between Plg and IL-6 levels in patients with sepsis." (PMID 36917195, 2023). "In the present study, we evaluated the accuracy and usefulness of CPD, NE-SFL and NE-WY, as biomarkers for culture-proven bacteremia in hospitalized patients, in comparison with the other commercialized sepsis biomarkers in Japan, including CRP, PCT, presepsin, and IL-6." (PMID 37324133, 2023). "This study showed that C21 might reduce levels of pro-inflammatory cytokines, including TNF-, IL-6, and TNF receptor, by modulating the PI3K/AKT signaling pathways, which can, in turn, reduce renal dysfunction during CLP-induced sepsis in male mice." (PMID 36937479, 2023). "Sepsis represents a systemic response where LPS interacts with host cell receptors, generating numerous pro-inflammatory cytokines: tumor necrosis factor-alpha (TNF-α), interleukin (IL)-1β, IL-6, IL-12, and inflammatory mediators (nitric oxide (NO))." (PMID 38203627, 2023). "In vivo, DPPC-based liposomes containing LAN, but not CHO, significantly attenuated sepsis-induced liver injury and systemic accumulation of IL-6, sTNFRI, and KC, three pCTS-L-inducible cytokines/chemokines known as surrogate markers of experimental sepsis." (PMID 37239992, 2023). "In addition, it has been also reported that XBJ effectively reduced circulating IL-1β, IL-6, and TNF-α in CLP rats within 12 h after sepsis." (PMID 37219401, 2023). "Another study considered IL-1β inferior at predicting sepsis when compared to CRP, TNF and IL-6." (PMID 36769133, 2023). "A randomized controlled trial on sepsis patients reported significant removal of IL-6 in pre- and post-adsorbers measurements; however, no significant reduction in systemic IL-6 levels by CytoSorb® therapy was found." (PMID 35806919, 2022). "This would explain why increased tacrolimus exposure is not observed in transplant patients with comparable CRP levels for, e.g., septicaemia, where IL-6 or other inflammatory mediators are not expected to be elevated." (PMID 35651879, 2022). "Ex vivo LPS treatment of whole blood from patients diagnosed with sepsis resulted in 10–20% decreases of TNF-α and IL-6 production compared to blood from patients without sepsis." (PMID 35167625, 2022). "Elevated inflammatory cytokines, such as TNF-α, IL-1β, and IL-6, during sepsis do not provide specific information regarding the development and severity of the disease, and hence considering them as specific disease clinical markers is not suitable." (PMID 35205254, 2022). "FTB treatment lowered the levels of CRP, IL-6, IL-1β, and TNF-α in rats with sepsis." (PMID 36408247, 2022). "Previously, numerous studies have examined the prognostic role of IL-6 concentration on intensive care unit (ICU) admission during sepsis, almost constantly finding a negative impact of high concentrations on survival." (PMID 35634339, 2022). "TAK-242 treatment in sepsis patients did not affect plasma IL-6 levels, indicating no overall change in inflammatory status of the patients." (PMID 35634305, 2022).